TTF1 (transcription termination factor 1)
Diseases named in the same sentence as TTF1 in open-access papers (continued):
Sharing a sentence is not in itself a finding about the gene and the disease.
lung adenocarcinoma (continued). "Moreover, IHC showed that PACC can express specific markers, including CD117, SMA, P63 and S-100, which is not the case for primary lung adenocarcinoma that is usually TTF-1 negative." (PMID 37198615, 2023). "In lung adenocarcinomas, TTF-1 is highly expressed in nonmucinous carcinomas, contributing to increased tumor cell proliferation and survival, and most squamous cell carcinomas of the lung do not express TTF-1, suggesting its utility in the diagnosis and differential diagnosis of lung cancer." (PMID 36614938, 2022). "However, pemetrexed‐based regimen has been inferior to nonpemetrexed‐based chemotherapy in lung adenocarcinoma patients with negative TTF‐1 expression in terms of PFS and OS." (PMID 35808895, 2022). "TTF-1 is typically negative but may be focally expressed in a subset of pulmonary NC that can be misidentified for lung adenocarcinoma." (PMID 36290813, 2022). "It has been reported that TTF‐1 negative lung adenocarcinoma had more frequent Kelch‐like epichlorohydrin‐associated protein 1 (KEAP1) mutations, which negatively affect ICI efficacy, than TTF‐1 positive lung adenocarcinoma." (PMID 35808895, 2022). "TTF-1 is expressed in nearly 75% of nonmucinous lung adenocarcinoma." (PMID 34631891, 2021). "Though lung adenocarcinoma was suspected, immunostaining for TTF‐1 was negative (data not shown)." (PMID 31631464, 2019). "Also, most lung adenocarcinomas have the same IHC profile with positive CK7, TTF-1 and napsin A." (PMID 28347348, 2017). "Thyroid transcription factor 1 (TTF-1) expression, as a lineage marker of the terminal respiratory unit, is helpful to distinguish the primary (TTF-1 positive) from the metastatic (usually TTF1 negative) lung adenocarcinoma, the pleural lung carcinoma (TTF-1 positive) from the mesothelioma." (PMID 28783064, 2017). "The TTF-1, miR33a and HMGA2 may have cross talk in regulation of the lung adenocarcinoma." (PMID 29079814, 2017). "While an exhaustive discussion is beyond the scope of this manuscript, suffice to indicate that most primary lung adenocarcinomas are CK7 and TTF-1 positive, although as previously noted, TTF-1 staining may also be seen in thyroid tumors and infrequently in tumors originating from other body sites." (PMID 22263108, 2012). "Whilst 80% of lung adenocarcinoma exhibits TTF-1 positivity, a positive TTF-1 stain in pleural fluid without an established primary cause may alternatively suggest primary non-small cell lung cancer." (PMID 22448326, 2012). "Immunohistochemical staining showed that the tumor cells were positive for thyroid transcription factor‐1 (TTF‐1) and keratin 7 (K7) but negative for keratin 20 (K20) and prostate‐specific antigen (Figure not shown), which supported the diagnosis of poorly differentiated lung adenocarcinoma." (PMID 40309045, 2026). "However, given TTF-1’s high specificity for lung adenocarcinomas, positive TTF-1 staining in metastatic lesions strongly suggests a primary lung adenocarcinoma, as opposed to a potential unknown tumor metastasizing to the lung." (PMID 40021683, 2025). "Additionally, the lung mass was histologically similar to the resected urachal carcinoma, with positive expression of CK7, CK20, Villin, and CDX2, and negative for GATA3, TTF1, and NapsinA, supporting the diagnosis of metastatic urachal carcinoma rather than primary lung adenocarcinoma." (PMID 39462217, 2024). "Although the present study did not assess the KEAP1 and/or STK11 gene alterations and the detailed types of adenocarcinomas, above‐mentioned reports might partially explain why TTF‐1 negative lung adenocarcinoma showed worse outcomes with ICI monotherapy in our study." (PMID 35808895, 2022). "However, lung squamous cell carcinoma does not express TTF-1, which is most commonly used to distinguish primary lung adenocarcinoma from other metastatic tumors, suggesting its important application value in the diagnosis and differential diagnosis of lung cancer.." (PMID 34631891, 2021).
lung adenocarcinoma (continued). "However, the patients in their researches were commonly with advanced diseases and the chemotherapeutic effect between TTF-1 positive adenocarcinoma and TTF-1 negative adenocarcinoma, especially in early-stage lung adenocarcinoma is unknown." (PMID 29296178, 2017). "Immunostains showed that the neoplastic cells with prominent nucleoli are positive for TTF‐1 and negative for CK20, supporting the diagnosis of lung adenocarcinoma." (PMID 40028792, 2025). "Thyroid transcription factor-1 (TTF-1) is a lineage-specific marker for lung adenocarcinoma (LUAD), whereas the relatively minor subset of TTF-1-negative LUADs shows a poor prognosis and a limited response to therapy." (PMID 40824335, 2025). "TTF-1, CK7, and Napsin A positivity on IHC confirmed lung adenocarcinoma, a disease increasingly seen in non-smokers due to factors such as genetic mutations (e.g., EGFR, ALK) and environmental exposures." (PMID 40821205, 2025). "Immunohistochemical analysis showed positive staining for CK (AE1/AE3), TTF-1, and p40, while CK56, CD68, CD45 (LCA), D2-40, and Ki-67 (50%+) were negative, leading to the diagnosis of lung adenocarcinoma." (PMID 39928773, 2025). "All the available tested thoracic SMARCA4-UT samples were negative for lung adenocarcinoma markers (CK7, TTF-1, and Napsin A) and for squamous cell carcinoma markers (p63, p40, and CK5&6)." (PMID 38374950, 2024). "IHC was positive for CK-7, TTF-1, and Napsin A, but negative for CK20 and CDX2, consistent with a primary lung adenocarcinoma." (PMID 39544293, 2024). "IHC on the surgical specimen showed positivity for CK7, TTF1, and Napsin A, and negative staining for CK20, consistent with primary lung adenocarcinoma." (PMID 39544293, 2024). "In particular, histochemistry showed positive for NapsinA and TTF-1, and negative for renal origin marker PAX-8 which proved it was lung adenocarcinoma metastases to the kidney." (PMID 37161448, 2023). "Given the low response rate of ICI monotherapy in patients without TTF‐1 expression in our study, the possibility of poor efficacy should be considered when treating TTF‐1 negative lung adenocarcinoma with ICI monotherapy." (PMID 35808895, 2022). "Gene expression of TTF1 was higher compared to the negative controls, but at an overall low expression and variance, suggesting that protein expression of TTF1 as the most important marker for adenocarcinoma of the lung may not be represented by high RNA levels." (PMID 32620126, 2020). "After initial immunohistochemical stainings and due to the therein reported expression of TTF1, CK7 and the lack of CK20, this diagnosis was changed to primary adenocarcinoma of the lung." (PMID 22269186, 2012). "Furthermore, approximately 70% of lung adenocarcinomas (LADs) express TTF‐1 independent of disease stage and retain features of the TRU to a certain extent, strongly suggesting that NKX2‐1/TTF‐1 is a potential lineage survival oncogene in lung cancer." (PMID 34014042, 2021). "Immunostaining of tumor cells were positive for thyroid transcription factor‐1 (TTF‐1) and cytokeratin 7 (CK7), while negative for caudal‐related homeobox transcription factor 2 (CDX‐2) and cytokeratin 20 (CK‐20), indicating a lung adenocarcinoma origin." (PMID 28781870, 2017). "Immunohistologically, the tumor cells were stained positive for cytokeratin 7 (CK7) in the cytoplasm and for thyroid transcription factor 1 (TTF-1) in the nucleus, but negative for cytokeratin 20 (CK20), suggesting that the tumor cells originated from either thyroid cancer or lung adenocarcinoma." (PMID 18801198, 2008). "In 2174 lung adenocarcinomas, SMARCA2-negative expression (n = 205) was significantly correlated with high-grade nuclei, eosinophilic staining of the cytoplasm, solid and micropapillary histological subtypes, TTF-1-negative expression and Napsin-A-negative expression (P < 0.05)." (PMID 35289322, 2022).
lung adenocarcinoma (continued). "TTF‐1 is expressed in 69%–80% of cases of nonsquamous non‐small cell lung cancer (NSCLC), and is commonly used to diagnose the histological type of lung cancer and distinguish primary lung adenocarcinoma from other metastatic adenocarcinomas in pathological cases." (PMID 35808895, 2022).
lung carcinoma (176 papers, 2006 to 2026). "Some of the selected antigens are used as diagnostic markers in lung cancer subtypes (TTF-1, MUC-1, HER, cytokeratin, and CD56), others as prognostic, proliferative, or immunosuppressive targets." (PMID 39941799, 2025). "This study indicated that TTF‐1 negativity was associated with disease progression in patients with lung cancer treated with PEM." (PMID 38485287, 2024). "No SGM-101 fluorescence, no CEACAM5 staining, and no other immunohistochemical staining were associated with markers of lung malignant neoplasms, including thyroid transcription factor 1 (TTF-1), cytokeratin 5/6 (CK 5/6), and p63 (eFigure 6 in Supplement 2)." (PMID 36705924, 2023). "Since the elevated expression of TTF-1 is associated with better survival of lung cancer patients 23, our study counted the percentage of TTF-1 positive cells in each group and tested its protein expression level in the lung." (PMID 35371324, 2022). "In the past few years, antidiuretic hormone (ADH), tumour necrosis factor alpha (TNF-α), NF-κB/p65, COX-2 and thyroid transcription factor-1 (TTF-1) have been reported to be associated with the prognosis of lung cancer." (PMID 32312252, 2020). "The TTF1+ xMD procured lung carcinoma cells demonstrated a 5-8-fold increase in KRAS mutation percentage in comparison to the whole cytospin macrodissection (46–76% vs. 9%)." (PMID 26999048, 2016). "In lung cancer, down-regulation of miR-365 has been implicated in increased expression of thyroid transcription factor 1 (TTf1), important for lung development and commonly up-regulated in lung tumors." (PMID 24029073, 2013). "The aim of the present study was to detect the expression of TTF-1 in human lung cancer cell lines and to evaluate the association of overexpressed TTF-1 with Ki-67 and apoptosis in the A549 cell line." (PMID 22940844, 2012). "TTF-1 negativity is associated with poor prognosis in lung cancer patients." (PMID 39421450, 2024). "TTF-1 is also associated with tumor differentiation and survival outcomes in lung cancer." (PMID 39456114, 2024). "Our tissue models were characterized by hematoxylin eosin staining, M30 enzyme-linked immunosorbent assay, and immunofluorescence staining against specific lung cancer markers (TTF-1 and p40/p63), cancer-associated fibroblast (CAF) markers (α-SMA and MCT4), and fibronectin (FN)." (PMID 38115596, 2024). "Furthermore, an interesting report suggested that lung cancer A549 cells with high expression of thyroid transcription factor 1 (TTF-1) associated with low cholesterol were more vulnerable to simvastatin." (PMID 39329956, 2024). "TTF-1 positivity could be a surrogate for EGFR mutations in driving oncogenicity in lung cancer patients." (PMID 31196060, 2019). "TTF‐1 (also known as thyroid transcription factor 1) and Mucin 5B have been described as lung differentiation markers associated with better prognostic outcome in lung cancer patients." (PMID 31268606, 2019). "Furthermore, thyroid transcription factor 1 (TTF-1) is routinely tested in the diagnostic evaluation of suspected lung cancers." (PMID 30956278, 2019). "The NKX2–1 locus, which encodes TTF-1, is frequently amplified in the lung cancer genome." (PMID 31196060, 2019). "In order to explore the underlying mechanism of TTF-1-promoter-operating miR-7 expression on the growth of lung cancer cells, we analyzed the global gene expression profile in tumor tissue between the p-T-miR-7 and the p-Cont injection group using gene expression microarray assay." (PMID 28325285, 2017). "The role of TTF‐1 may be associated with the occurrence of lung cancer." (PMID 35808895, 2022). "Combined, these findings suggest that TTF1 protein expression (a routine clinical diagnostic IHC marker for lung cancer) could be a surrogate marker for DLL3 expression and, thus, help identify patients with DLL3-positive tumors (which have the highest response rates to rovalpituzumab tesirine)." (PMID 29088717, 2017).
lung carcinoma (continued). "Immunohistochemical analysis of the gastric lesion demonstrated TTF-1 positivity, leading to the diagnosis of gastric and adrenal metastatic recurrence of lung cancer." (PMID 41635529, 2026). "Non-small cell lung cancer (NSCLC) that co-expresses thyroid transcription factor-1 (TTF-1) and p40 represents a distinct subtype of lung cancer." (PMID 39928773, 2025). "Literature notes that some mediastinal CUP cases with lymph node involvement exhibit a lung cancer profile on IHC, such as TTF-1 positivity, and are staged as N2 lung cancer with an occult primary." (PMID 40585691, 2025). "For example, immunohistochemical profiling (TTF-1+/NapsinA+ in lung cancer, CK20-/CDX-2- in ovarian cancer) and site-specific pathological features were critical for confirming the independence of the four tumors." (PMID 41584613, 2025). "Previous studies have revealed that the expression of the NKX homeobox-1 (NKX2-1) gene, also referred to as thyroid transcription factor-1 (TTF-1), is a specific biomarker of lung carcinomas." (PMID 41415280, 2025). "In lung cancer, the expression levels of TTF-1 (n=9, 81.82%), CK7(n=8, 88.89%), CKAE1(n=5, 100%), and CKAE3(n=5, 100%) were relatively high." (PMID 40313249, 2025). "IHC stains, such as CK7, TTF-1, and napsin A, aid in identifying the tumor's origin and subtype, distinguishing it from other lung cancers and metastatic lesions." (PMID 40524907, 2025). "In conclusion, poorly differentiated NSCLC with TTF-1/p40 co-expression can be a novel type of lung cancer." (PMID 39928773, 2025). "The combination of p40 positivity (a recent molecular marker with reported 100% specificity and high sensitivity for squamous cell lung carcinoma), and thyroid transcription factor-1 (TTF-1) negativity confirmed the squamous lineage of lung cancer." (PMID 41210693, 2025). "So far only one study published in 2023 on 137 patients with NSCLC/ADC brain metastases assessed the role of TTF-1, which was exclusively based on lung tissue biopsies at the time of diagnosed lung cancer." (PMID 39630375, 2025). "NKX2-1, also known as TTF-1, is a lineage-specific transcription factor involved in the occurrence of lung cancer and regulate the adeno-to-squamous transdifferentiation to determined tumor phenotype." (PMID 38708353, 2024). "TTF-1, indeed, has been suggested to reprogramme lung cancer secreted proteome into an antiangiogenic state." (PMID 37775725, 2024). "Of the antibodies used in humans, TTF-1 is the best characterized and studied in dogs to differentiate lung carcinoma from another type of metastatic carcinomas." (PMID 39902337, 2024). "TTF-1 is frequently expressed in lung cancer and serves as an important marker to distinguish primary lung adenocarcinomas from other metastatic tumors." (PMID 39456114, 2024). "For immunostainings, we used the most common lung cancer markers TTF-1 for ADC and p40/p63 for SQCC according to the corresponding pathology report." (PMID 38115596, 2024). "TTF-1 is involved in several aspects of lung cancer, including genetic changes, tumor growth, metabolism, and the secretion of certain proteins." (PMID 39044884, 2024). "This study evaluates the efficacy of a minimal panel immunostaining technique using immunohistochemical markers like napsin A, thyroid transcription factor 1 (TTF-1), p63, and synaptophysin to improve the precision of lung carcinoma subclassification." (PMID 39070322, 2024). "Its role in both promoting and inhibiting cancer, along with its participation in key biological processes, positions TTF-1 as an important element in the study of lung cancer and as a possible focus for treatments." (PMID 39044884, 2024). "We now report that those LXRαβ-/- mice, which live to 18-months of age, spontaneously develop a second type of lung cancer resembling a rare subtype of NSCLC (TTF-1 and P63-positive)." (PMID 37324952, 2023).